ENSG00000253085
Synonyms: LOC124900446
Gene: Small Cajal body-specific RNA gene on chromosome 1 (13,696,070 to 13,696,199, reverse strand). Ensembl gene ENSG00000253085.
Gene Ontology:
Biological process: RNA processing
Cellular component: Cajal body; nucleolus
Homologues: Paralogues in human: SCARNA11 (71% identical).